ITPRIPL1 (ITPRIP like 1)
Diseases named in the same sentence as ITPRIPL1 in open-access papers (continued):
Sharing a sentence is not in itself a finding about the gene and the disease.
tumor (continued). "Through analysis of TCGA data, we showed the expression levels of the ITPRIPL1 gene from a pan-cancer perspective and found statistically significant differences in expression levels between tumor tissues and correspond normal tissues across 13 common malignancies." (PMID 39211744, 2024). "However, there are discrepancies, such as its dual role as a risk and protective factor in different cancer types, indicating a complex, context-dependent function of ITPRIPL1 in tumor biology." (PMID 39211744, 2024). "Furthermore, the expression of ITPRIPL1 highly correlates with the presence of tumor-infiltrating immune cells and immune checkpoint genes across various types of cancers." (PMID 39211744, 2024). "The ITPRIPL1 expression was positively correlated with tumor stages." (PMID 38188019, 2023). "Moreover, the analysis of patients’ clinical information reveals a positive correlation between ITPRIPL1 expression and tumor stages." (PMID 38188019, 2023). "To further determine the origin of circulating methylated CCDC181, GCM2 and ITPRIPL1, we analyzed whether the DNA methylation between plasma and matched tumor tissues showed a similar pattern." (PMID 33803633, 2021). "Notably, the primary immune cluster with ITPRIPL1 enrichment within tumor tissues was MAIT T cells, the upregulation of which may promote tumorigenesis by suppressing T cells and NK cells." (PMID 38188019, 2023). "Additionally, the IHC staining of ITPRIPL1 in tumor tissues is relatively more homogenous, which could assist in delineating the precise boundaries of solid tumors." (PMID 38188019, 2023). "Therefore, ITPRIPL1 is indicative of more aggressive tumor progression and poorer prognosis." (PMID 38188019, 2023). "The extracellular domain of ITPRIPL1 directly binds to the CD3ε extracellular domain, inhibiting TCR‐CD3 signaling and hindering the initial activation of T cells, thus promoting tumor immune escape and progression." (PMID 40528483, 2025). "In our study, we used a set of 96 tumor samples of less than 2 cm; in this set, the assessment of the methylation of the GCM2, ITPRIPL1, CACNA1E, and DLGAP2 genes most accurately distinguished cancer from healthy tissues." (PMID 37628841, 2023). "In our previous studies, we discovered that cancer cells upregulate inositol 1,4,5-triphosphate receptor-interacting protein-like 1 (ITPRIPL1), a natural CD3 ligand, to evade immune surveillance and promote tumor growth." (PMID 38188019, 2023). "Inositol 1,4,5-triphosphate receptor-interacting protein-like 1 (ITPRIPL1), a single-transmembrane protein, has been identified as a natural ligand of CD3ε to downregulate T cell function and promote tumor growth in our previous study (submitted)." (PMID 38188019, 2023). "Despite increasing evidence suggesting that ITPRIPL1 plays a significant role in tumor growth, no systematic pan-cancer analysis of ITPRIPL1 has been conducted to date." (PMID 39211744, 2024). "Our data, combined with results from the ProteinAtlas database indicated the upregulation of ITPRIPL1 signal in NSCLC tumors is largely due to the overexpression of this marker in tumor cells rather than in stromal cells within the tumor microenvironment." (PMID 38188019, 2023). "The positive correlation between ITPRIPL1 expression and tumor stages suggests a negative correlation between ITPRIPL1 and prognosis." (PMID 38188019, 2023). "The high immunohistochemical positivity of ITPRIPL1 in NSCLC tumor samples with negative staining in most normal lung tissues suggests potentially better sensitivity and specificity." (PMID 38188019, 2023). "Respectively, the expression of CDO1, CELF2, ITPRIPL1, KCNH8, RIC3, USP44 and ZSCAN23 was significantly lower in tumor tissues, whereas the expression of PTK6 and RAB25 was significantly higher in tumor tissues." (PMID 34056873, 2021).
tumor (continued). "Recent studies have found that ITPRIPL1 is commonly observed in tumors with low expression of PD-L1 and the expression of this gene can inhibit T cells in the tumor microenvironment (TME), while antibodies targeting this gene can suppress tumor growth and promote T cell infiltration." (PMID 39211744, 2024). "However, in other tumor types, we did not observe significant differences in ITPRIPL1 mRNA expression levels across different clinicopathological stages (P > 0.05)." (PMID 39211744, 2024).
cancer (7 papers, 2021 to 2025). A tumor composed of atypical neoplastic, often pleomorphic cells that invade other tissues. "We employed the Gene Set Cancer Analysis (GSCA) database to analyze the potential associations between ITPRIPL1 expression and Genomic alterations and DNA methylation across 33 types of cancer." (PMID 39211744, 2024). "In summary, our findings further confirmed that ITPRIPL1 holds promise as a prognostic biomarker across various cancers and as a predictive indicator for immunotherapy." (PMID 39211744, 2024). "Future research should focus on these aspects to fully elucidate the role of ITPRIPL1 in cancer biology and therapy." (PMID 39211744, 2024). "The results from different analyses show some consistency, particularly in the cancer types where ITPRIPL1 expression is either elevated or reduced and its impact on prognosis." (PMID 39211744, 2024). "We observed that ITPRIPL1 expression was associated with TMB in 6 cancer types and with MSI in 13 cancer types." (PMID 39211744, 2024). "Using the CIBERSORT, MCPcounter, and ssGSEA algorithms, we explored the relationship between ITPRIPL1 expression and the infiltration levels of different immune cells in the 33 cancer types." (PMID 39211744, 2024). "Based on all these results, we unveiled a correlation between ITPRIPL1 expression and immune response, suggesting its potential as a promising prognostic biomarker across various cancers." (PMID 39211744, 2024). "High expression of ITPRIPL1 serves as a protective factor in certain cancer types, correlating with longer overall survival in BRCA." (PMID 39211744, 2024). "Our research endeavors to offer further elucidation on the significance of ITPRIPL1 across different cancer types." (PMID 39211744, 2024). "Our study further confirms that ITPRIPL1 participates in regulating immune infiltration and affecting the prognosis of patients in pan-cancer." (PMID 39211744, 2024). "This study conducted a comprehensive pan-cancer analysis of ITPRIPL1 expression by integrating data from multiple databases, including TCGA, GTEx, and HPA, through various bioinformatics analysis methods." (PMID 39211744, 2024). "Univariate cox regression analysis was utilized to explore the association between OS, DSS, DFI and PFI and the mRNA expression levels of ITPRIPL1 in pan-cancer." (PMID 39211744, 2024). "We employed the CIBERSORT, MCPcounter, and ssGSEA algorithms to explore the relationship between ITPRIPL1 expression and the infiltration levels of different immune cells in the 33 cancer types." (PMID 39211744, 2024). "The database showed upregulated ITPRIPL1 mRNA expression in different cancers, and we confirmed the overexpression of ITPRIPL1 at the protein level, especially in tumors from NSCLC patients." (PMID 38188019, 2023). "In sum, ITPRIPL1 has the potential as a proteomic immunohistochemical cancer biomarker for future clinical concerns, the positive rate of which can suggest the level of CD8 positive T cell infiltration and clinical outcome prognosis." (PMID 38188019, 2023). "We found that the ITPRIPL1 expression level was positively correlated with cancer stages and negatively correlated with CD8+ T cell infiltration, which indicated poorer clinical outcomes." (PMID 38188019, 2023). "The upregulation of ITPRIPL1 in cancers indicates less sensitivity to the existing immunotherapy, likely related to immune evasion." (PMID 38188019, 2023). "The wide overexpression of ITPRIPL1 in cancers made it valuable for assessing tumorigenesis and immune infiltration." (PMID 38188019, 2023). "The expression level was consistent with the transcriptomic datasets from the Cancer Cell Line Encyclopedia (CCLE) concerning the ITPRIPL1 mRNA levels in different human cancer cell lines and our previous studies." (PMID 38188019, 2023).
cancer (continued). "ANKRD36 has been reported to be coexpressing and interacting with other genes on locus 2q11.2, including ANKRD36C, ITPRIPL1, FAHD2B, FAM178B and CNNM3, which shows that ANKRD36 is involved in some important biological networks associated with cancers." (PMID 34827175, 2021). "However, research on ITPRIPL1, particularly exploring its potential roles in various human cancer types using multi-omics data, is currently inadequate." (PMID 39211744, 2024). "The results indicate that ITPRIPL1 might be crucial in controlling immune cell infiltration in some cancer types." (PMID 39211744, 2024). "We observed the ITPRIPL1 expression is strongly associated with activated memory CD4+ T cells, CD8+ T cells, regulatory T cells (Tregs), M1 macrophages, NK cells and activated dendritic cells in some cancer types." (PMID 39211744, 2024). "Additionally, ITPRIPL1 expression was associated with TMB in 6 cancer types and with MSI in 13 cancer types." (PMID 39211744, 2024). "Interestingly, these results indicated that ITPRIPL1 expression levels are strongly correlated with prognosis in some cancers like LGG." (PMID 39211744, 2024). "We performed ROC analysis and calculated the AUC values of the ITPRIPL1 gene, plotting the ROC curves for the three cancers with high accuracy (AUC >0.7), specifically: BRCA (AUC = 0.961,CI 0.942–0.976), KICH (AUC = 0.716,CI 0.6–0.811), and PRAD (AUC = 0.857,CI 0.799–0.907)." (PMID 39211744, 2024). "This study utilized datasets curated from The Cancer Genome Atlas, Genotype Tissue-Expression, and Human Protein Atlas to investigate the relationship between ITPRIPL1 expression and clinical outcomes, immune infiltration, and drug sensitivity across 33 cancer types." (PMID 39211744, 2024). "The results indicated overexpression of ITPRIPL1 in various human cancer cell lines." (PMID 38188019, 2023). "However, little is known of the function and mechanism of ITPRIPL1 in cancer research." (PMID 34056873, 2021). "Drug sensitivity analysis and molecular docking were conducted based on data from Gene Set Cancer Analysis (GSCA), Genomics of Drug Sensitivity in Cancer (GDSC), UniProt, and PubChem databases to explore the therapeutic potential of ITPRIPL1 as a drug target." (PMID 40792394, 2025). "We utilized the GSCA database to examine the correlation between ITPRIPL1 expression levels and CNV and methylation in pan-cancer." (PMID 39211744, 2024).
ITPRIPL1 also shares sentences with these, for which no sentence is quoted: colorectal cancer (2 papers); acute myeloid leukemia (1); cholangiocarcinoma (1); diffuse large B-cell lymphoma (1); ductal carcinoma in situ (1); esophageal carcinoma (1); esophagus cancer (1); Fibroadenoma (1); gastric cancer (1); glioblastoma (1); head and neck squamous cell carcinoma (1); kidney chromophobe (1); liver cancer (1); lung squamous cell carcinoma (1); lymph node metastasis (1); melanoma (1); non-small cell lung carcinoma (1); ovarian carcinoma (1); pancreatic adenocarcinoma (1); pancreatic cancer (1); pheochromocytoma and paraganglioma (1); prostate adenocarcinoma (1); rhabdomyosarcoma (1); skin cutaneous melanoma (1); stomach adenocarcinoma (1); testicular germ cell tumor (1); thyroid carcinoma (1); uterine cancer (1); uterine carcinosarcoma (1).